MERTK (MER proto-oncogene, tyrosine kinase)
Diseases named in the same sentence as MERTK in open-access papers (continued):
Sharing a sentence is not in itself a finding about the gene and the disease.
tumor (196 papers, 2013 to 2026). "As MerTK is directly linked to MΦ M2 polarization and immunosuppression, our finding suggests a new mechanism for enhancing tumor immunosuppression." (PMID 39941817, 2025). "High MERTK expression in tumor‐associated macrophages correlated with multiple cancer‐related pathways, as indicated by KEGG and GO analyses." (PMID 40433916, 2025). "One major issue is the broad expression of TAM receptors (Tyro3, Axl, MerTK) across both tumor and normal tissues, which increases the risk of off-tumor effects such as impaired clearance of apoptotic cells and autoimmune-like toxicities." (PMID 40821795, 2025). "Beyond kinase inhibition, MERTK-expressing macrophages have been linked to tumor progression and resistance to immunotherapy, and targeting MERTK signaling in macrophages has been shown to improve responses to immune checkpoint blockade." (PMID 41166341, 2025). "Myeloid-epithelial-reproductive tyrosine kinase (MERTK) is a tyrosine kinase receptor of the tumor-associated macrophage (TAM) family." (PMID 41166341, 2025). "The mechanisms underlying PROS1 activation in adi‐CAFs and MERTK activation in tumor cells were also investigated." (PMID 40433916, 2025). "MIC-1 (GDF15) and GRN are associated with tumor-induced immune tolerance and inflammation, while MERTK is a receptor tyrosine kinase involved in the clearance of apoptotic cells and immune suppression." (PMID 40805206, 2025). "Single‐cell data further supported the upregulation of MERTK in thyrocytes, particularly in clusters 2, 3, 6, and 7, which are associated with tumor progression." (PMID 40433916, 2025). "In contrast, within the tumor microenvironment, tumor‐derived factors upregulate Axl and MerTK, and such overexpression is linked to immune evasion and treatment resistance, as has been reported for bladder cancer and other malignancies." (PMID 41403915, 2025). "MerTK is widely expressed in many cell types, including tumor cells and normal cells of hematopoietic lineage, and MerTK specifically has been implicated in the progression of many hematological and solid tumor malignancies." (PMID 38791148, 2024). "Studies have implicated the overexpression of MERTK in GBM cells as a contributing factor to the tumor’s invasive capabilities and its resistance to programmed cell death, or apoptosis." (PMID 39062902, 2024). "The ASO significantly reduced the expression of MerTK in tumor-associated macrophages (TAMs), reprograming their phenotype from M2 to M1." (PMID 38443968, 2024). "Mice harboring MERTK-deficient myeloid cells showed tumor resistance, slower tumor growth, and enhanced expression of inflammatory cytokines, accompanied by higher presence of CD8 T cells." (PMID 38573347, 2024). "The authors observed in two mouse models of cancer (MC38, colon adenocarcinoma; and E0771, triple negative breast cancer) that blocking MerTK mediated efferocytosis by tumor associated macrophages causes release of cGAMP from dying cells." (PMID 37287967, 2023). "The prepared mU@OMVs effectively inhibits the efferocytosis by promoting the uptake while preventing the MerTK phosphorylation of tumor associated macrophages, and then captures the released antigens through forming universal thioether bonds." (PMID 36966130, 2023). "Here the authors developed a nanosystem that inhibits MerTK-mediated efferocytosis and captures tumor-associated agents to enhance antitumour immunity." (PMID 36966130, 2023). "It was also suggested that blockade of MERTK-dependent phagocytosis in tumor-associated macrophages activated the STING pathway." (PMID 35969037, 2022). "Of note, the expression of TYRO3, AXL, and MERTK, as well as their ligands, can be dramatically upregulated on immunosuppressive MDSCs in Braf-V600E/Pten deficient melanoma tumor-bearing C57BL/6 mice." (PMID 35572601, 2022). "MerTK has also been reported to increase the M1 to M2 ratio in tumor-associated macrophages and microglial cells." (PMID 36225585, 2022).
tumor (continued). "CT053PTSA is a potent inhibitor of MET, AXL, VEGFR-2, FMS-like tyrosine kinase 3 (FLT3) and MERTK, all of which have been implicated in tumor pathogenesis." (PMID 36341335, 2022). "Since we did not test identical tumor models as the previous reports, it remains entirely possible that anti-tumor immunity in the models reported before, serendipitously, is dependent exclusively on the loss of MERTK." (PMID 35969037, 2022). "The gene encoding this receptor, was also found to be upregulated in TBX19 tumors, as was the gene encoding MERTK which seems to play an important role in tumor proliferation, survival and migration." (PMID 35260162, 2022). "In a model of colitis-associated colon cancer, Axl-/-MerTK-/- mice surprisingly exhibited enhanced tumor growth due to the inability of macrophages to clear the microenvironment from apoptotic neutrophils." (PMID 34771611, 2021). "TAMs that express MerTK are also associated with tumor growth and resistance to treatment, making MerTK a potential therapeutic target." (PMID 32322199, 2020). "MerTK on tumor associated macrophages has been shown to play a role in radiation therapy resistance." (PMID 31088471, 2019). "Following radiation therapy in a colorectal cancer mouse model, MerTK, Protein S and Gas6 are upregulated in tumor associated macrophages." (PMID 31088471, 2019). "The TAM receptors (Tyro3, Axl and MerTK) are promising therapeutic targets on tumor-associated macrophages." (PMID 31088471, 2019). "Tumor histology and vascularity were similar between lung tumors from WT and MerTK deficient mice; however, by PCNA immunofluorescence, tumor cell proliferation was significantly reduced in tumors from MerTK deficient mice." (PMID 31903163, 2019). "Several studies show that tumor associated macrophages use MerTK signaling to produce a more agressive and tolerogenic tumor microenvironment." (PMID 30187085, 2018). "In order to evaluate long-term effect of MerTK depletion combined with vemurafenib treatment, we treated the mice bearing MerTK-deficient tumours with PLX for 8 weeks once daily." (PMID 29050198, 2017). "All patients showed alterations in one to three genes frequently described as drivers in HNSCC suggesting that MERTK mutations are rather passenger mutations in this tumor entity." (PMID 27081701, 2016). "This is most likely due to the fact that MERTK expression is associated with the location of the primary tumor and shows a significant relationship to tumor stage and N status, which are strong determinants for patient survival." (PMID 27081701, 2016). "Given that MerTK is highly expressed in about one-third of human TNBCs and MerTK overexpression is linked to tumor progression in vitro, we hypothesized that tumors overexpressing MerTK would grow faster in vivo and lead to an immunosuppressive TIME." (PMID 40391157, 2025). "Moreover, MERTK expression was detected in tumor‐associated macrophages, with significant upregulation observed in stages II and III tissues." (PMID 40433916, 2025). "In addition, overexpression of YAP1 induces the polarization of macrophages into the M2 phenotypes (tumor-associated macrophages) by regulating different genes such as iNOS, MerTK, IL-10, STAT3, CD163, CD206, Arg-1, CD86, and TNF-α in the naive macrophages." (PMID 39630608, 2024). "MerTK has previously been implicated in cancer cell invasion and tumor metastasis." (PMID 38791148, 2024). "The Tyro3, AXL, and MerTK (TAM) receptor family regulate tumor-associated macrophages that elicit an immunosuppressive tumor microenvironment, and blockade of TAM receptors via cabozantinib may invigorate antitumor immune activation." (PMID 36969746, 2022). "Mutational inactivation of BAP1 in UM may lead to a suppressive TIME at least in part by upregulation of PROS1 in tumor cells and phospho-activation of MERTK in tumor-associated macrophages." (PMID 35954340, 2022).
tumor (continued). "Furthermore, an excellent study revealed that blockade of phagocytic receptor MERTK on tumor-associated macrophages augmented tumor immunogenicity and potentiated anti-tumor immunity via inducing tumor-cGas and host-STING-dependent type I interferon response." (PMID 35281078, 2022). "In murine models, compared with traditional radiotherapy, anti-PD-1 therapy relieves the inhibitory effect on immune cells such as TRM cells, while anti-MerTK can transform apoptosis caused by radiation into cell necrosis and turn macrophages near tumors from M2 to M1 and reduce tumor load." (PMID 34707601, 2021). "The investigators hypothesized that these effects are mediated by inhibition of MerTK, a tyrosine kinase receptor that when activated contributes to an immune tolerant tumor microenvironment via the regulation of phagocytosis by tumor‐associated macrophages." (PMID 32400122, 2020). "Additionally, MerTK deficiency shows better tumor control after radiotherapy in colorectal and pancreatic adenocarcinoma mice." (PMID 32802188, 2020). "Furthermore, in MerTK−/− mice tumor models, efferocytosis is impaired leading to the decrease of immunosuppressive cytokines associated with tumor growth." (PMID 33101282, 2020). "This suggests that targeting MerTK on tumor associated macrophages may impair resistance following radiation therapy." (PMID 31088471, 2019). "While several somatic mutations of MerTK were found in certain cancers, it is believed that their functional role is limited, and ectopic expression or overexpression seems to be the major pathogenesis in various neoplasms." (PMID 29228560, 2017). "We showed that high MERTK expression was associated with stage T4 tumours." (PMID 29101300, 2017). "Therefore, inhibiting MERTK may play a role in reversing tumor-associated macrophages to an M1-like phenotype." (PMID 33425754, 2020). "Conversely, efferocytosis of apoptotic tumor cells activates MerTK and Axl signaling pathways, resulting in STAT3 phosphorylation and increased production of IL-10 and TGF-β." (PMID 41373540, 2025). "Since AXL/MERTK are mainly expressed in mouse Reg-TAMs, we conducted flow cytometry to examine tumor-infiltrated macrophages." (PMID 39774471, 2025). "The in vivo data presented thus far suggests a potential role for tumor-bound MerTK as a predictive biomarker for TNBC response to ICIs." (PMID 40391157, 2025). "While the role of the TAM family of RTKs expressed on macrophages and dendritic cells has been studied, the role of tumor-bound MerTK in the tumor immune microenvironment is poorly understood." (PMID 40391157, 2025). "This process regulates MERTK-induced cell death and immune equilibrium, ultimately promoting tumour progression." (PMID 40088262, 2025). "The observed increase in elevation suggests a potential role of MERTK in promoting tumor proliferation and metastasis." (PMID 41166341, 2025). "Specifically, Hsp70, secreted by cancer cells, interacted with toll-like receptor 2 (TLR2) and triggered Mer receptor tyrosine kinase (MerTK) upregulation to stimulate MΦ M2 polarization and tumor growth." (PMID 39941817, 2025). "Axl, a member of the TAM family of RTKs (Tyro3, Axl, and MerTK), has been extensively studied for its tumor-intrinsic mechanisms in driving HNC progression." (PMID 40149328, 2025). "MERTK was primarily expressed in myeloid cells and tumor epithelial cells in stages II and III tissues." (PMID 40433916, 2025). "Disruption of Axl and MerTK signaling with the small molecule inhibitor INCB081776 slowed HNC tumor growth, led to the development of a pro-inflammatory TIME, and enhanced tumor response to immunotherapies." (PMID 40149328, 2025). "Our group has previously reported that in in vitro and immunodeficient mouse models of TNBC, MerTK overexpression promotes cell proliferation and contributes to tumor progression and metastasis." (PMID 40391157, 2025).
tumor (continued). "We chose the EMT6 MerTK C5 clone to carry out experimentation on due to the robust increase in MerTK expression following the addition of dox and its ability to establish a tumor in syngeneic mice." (PMID 40391157, 2025). "Flow cytometry, immunohistochemistry, RNA, multiplex ELISA, immunohistochemistry and multiplex immunofluorescence analysis were used to probe the effects of MerTK expression on the tumor immune microenvironment." (PMID 40391157, 2025). "Significantly increased staining of CD8+ T cells, CD4+ T cells, macrophages (F4/80), and NK cells (NKp46) in EMT6 MerTK C5 + dox tumor sections was observed compared to EMT6 Vector + dox and EMT6 MerTK C5 fed regular diet." (PMID 40391157, 2025). "Various blood cancers, including acute lymphoblastic leukaemia and acute myeloid leukaemia (AML), also exhibit elevated MERTK expression, with its expression crucial for tumour cells to evade innate immune surveillance." (PMID 40088262, 2025). "Recent advances have underscored MERTK as a promising therapeutic target owing to its role in tumor cell survival, immune evasion, and macrophage-mediated immunosuppression." (PMID 41166341, 2025). "To further explore the link between MerTK expression and anti-tumor immune infiltrate, we utilized an inducible model of MerTK overexpression in the EMT6 model." (PMID 40391157, 2025). "We find that the previously observed increase in efferocytic macrophages within tumours and draining lymph nodes was reversed following MERTK inhibition." (PMID 39788719, 2025). "We identified CCL8 as a critical mediator of the GAS6/AXL/MERTK pathway, primarily by inhibiting Treg infiltration into the tumor." (PMID 39774471, 2025). "Key interactions between cancer‐associated fibroblasts (CAFs), tumor cells expressing PROS1, and tumor cells expressing MERTK were identified as central drivers of PTMC progression." (PMID 40433916, 2025). "We identifies WNT-activated tumor-initiating cells evading immune attacks by interacting with macrophages through the GAS6/AXL/MERTK pathway, suggesting new targets for cancer therapy." (PMID 39774471, 2025). "Although the molecular mechanism by which STK38 contributes to the tyrosine phosphorylation of MerTK is not yet fully understood, our findings provide further understanding and imply a new target for tumor metastasis therapy." (PMID 41226428, 2025). "As such, MerTK and Axl are central to establishing and sustaining a tolerogenic, tumor-permissive environment." (PMID 40821795, 2025). "In vivo subcutaneous implantation also demonstrated that tumors injected with PROS1‐overexpressing K1 cells were significantly larger than those in the NC group, with MERTK knockdown in K1 cells reducing the tumor growth driven by PROS1 overexpression." (PMID 40433916, 2025). "Our previous study demonstrated that Hsp70, secreted by cancer cells, interacts with toll-like receptor 2 (TLR2) and triggers the upregulation of MerTK, thereby stimulating M2 MΦ polarization and contributing to tumor growth." (PMID 40227806, 2025). "In this study, we also show that MerTK plays a unique role in the human tumor immune microenvironment in in vitro models and clinical biospecimens, and targeting MerTK as a therapeutic modality in TNBC should be considered with caution." (PMID 40391157, 2025). "MerTK overexpression in 4T1 and EMT6 tumors was associated with strong anti-tumor immune infiltration." (PMID 40391157, 2025). "Overexpression of MerTK in TNBC syngeneic mouse models leads to a marked delay in tumor growth, coupled with significant increases in anti-tumor M1 macrophage, CD4+ T cell, active CD8+ T cell, active NK cell, and NKT cell populations." (PMID 40391157, 2025). "MERTK inhibitors have demonstrated the ability to promote tumor cell apoptosis and enhance the efficacy of immunotherapy in several cancer models." (PMID 40433916, 2025).
tumor (continued). "Our group has previously demonstrated that overexpression of tumor-bound MerTK in TNBC promotes tumor progression and metastatic potential in in vitro and immunodeficient mouse models." (PMID 40391157, 2025). "To investigate TIC-derived GAS6 suppression of tumor immunity via AXL/MERTK on Reg-TAMs, we used Krt19-DreER Axin2-creER R26-Ai66 mice for AKT/YAP/SB hydrodynamic injection and sorted Reg-TAMs and epithelial cell adhesion molecule+/Tom+ (EpCAM+Tom+) TICs." (PMID 39774471, 2025). "The spatial expression and distribution of PROS1 and MERTK on H&E pathological sections aligned with single‐cell analysis, showing their primary distribution in tumor areas and increased expression as PTC progressed." (PMID 40433916, 2025). "Mice bearing EMT6 tumors were started on 200mg/kg dox chow 7 days prior to tumor inoculation and continued throughout the study to induce tumor MerTK expression." (PMID 40391157, 2025). "MERTK, on the other hand, is predominantly expressed in myeloid cells and tumor epithelial cells of progressive PTMC and PTC, with little to no expression in normal tissues and non‐progressive PTMC." (PMID 40433916, 2025). "Preclinical studies have demonstratedits promising efficacy in targeting MerTK-mediated tumor growth andimmune suppression." (PMID 40391976, 2025). "Quercetin effectively modulates MerTK‐mediated signaling pathways, reducing tumor progression, angiogenesis, and immune evasion." (PMID 41195524, 2025). "While MerTK seems to play opposing roles across tumor types, this finding exemplifies the ability of signaling pathways to behave differently in different contexts." (PMID 40391157, 2025). "In solid tumors, MerTK expression correlates with increased signaling through Akt, mTOR, and MEK/Erk and has been implicated in promoting tumor cell migration and invasion." (PMID 40391157, 2025). "In the tumor microenvironment, the expression level of MerTK is closely related to immune escape, mainly involving the functional regulation of tumor-associated macrophages (TAMs)." (PMID 40297581, 2025). "Though further validation is required, this preclinical study identifies tumor MerTK as a potential predictive biomarker to widen the cohort of patients eligible for ICI therapy." (PMID 40391157, 2025). "Dual treatment of these cell lines with bemcentinib and UNC2025, a MerTK-directed TKI, significantly inhibited tumor cell expansion in vitro and impacted tumor growth in vivo compared with single inhibition of Axl or MerTK alone." (PMID 39457986, 2024). "The inhibition of MerTK increases tumor immunogenicity and potentiates anti-tumor immunity, enhancing cancer immunotherapy." (PMID 38891056, 2024). "The TAM (Tyro3, Axl, MerTK) family of RTKs has been shown to provide cancer cells with a strong advantage in proliferation and survival, leading to tumor progression." (PMID 38791148, 2024). "In summary, our investigation revealed that MerTK regulates a unique proliferative signature, allowing for robust tumor growth and increased metastatic potential via the regulation of ENG." (PMID 38791148, 2024). "One of the key mechanisms by which MERTK promotes tumor survival and invasion is through its autophosphorylation in the kinase domain." (PMID 39062902, 2024). "Inhibiting the MerTK can reverse the immunosuppressive state induced by efferocytosis and has been shown to suppress tumor growth in various cancers." (PMID 39544291, 2024). "MERTK is also expressed on macrophages and other innate immune cells where it can function to suppress anti-tumor immunity." (PMID 39199601, 2024). "Mice received either anti-PD-1, anti-CTLA-4 or/and MerTK ASO starting from day 1 post tumor implantation." (PMID 38443968, 2024). "In this regard, we found that MerTK is highly expressed in activated plasma B cells under the tumor microenvironment, which have an expression level similar to macrophages." (PMID 38341954, 2024).